IL1B (interleukin 1 beta)
Diseases named in the same sentence as IL1B in open-access papers (continued):
Sharing a sentence is not in itself a finding about the gene and the disease.
endometriosis (continued). "Our results revealed that HMGB-1 was upregulated in ectopic endometrium, which was also positively correlated with inflammatory cytokines IL-6, TNF-α, and IL-1β, as well as autophagy-related protein beclin-1, suggesting that HMGB-1 might be involved in endometriosis." (PMID 33815277, 2021). "Tumor necrosis factor-alpha (TNF-α), interleukin one beta (IL-1β), and interleukin six (IL-6) are all elevated as well as the angiogenic factors (VGEF), the growth factors, and adhesion molecules all of which play a positive role in the occurrence, maintenance, and progression of endometriosis." (PMID 33354460, 2020). "Moreover, transient inhibition or reduction of miR-223 expression exacerbated endometriosis, as indicated by the histological indices, increased NLRP3, IL-1β, IL-6, and TNF-α secretion, as well as the IL-1β-inducible chemokines CXCL1 and CXCL2 mRNA transcripts." (PMID 30186287, 2018). "As a competitive antagonist for IL-1β, IL-1RA is detected in eutopic endometrium but is completely decreased in peritoneal fluid or absent in ectopic endometrium of patients with endometriosis." (PMID 20181040, 2010). "The link of IL1B protein expression with neurogenesis and with stromal cell migration and invasion, suggests IL1 receptor antagonist treatment could have pleiotropic effects on lesions, rendering this a particularly attractive therapeutic strategy for endometriosis." (PMID 40938538, 2025). "Furthermore, since treatment with IL-1β increased WEE1 expression levels in ESCs, modulation of WEE1 in response to inflammatory signals may provide an additional strategy for limiting fibrosis during endometriosis." (PMID 34686198, 2021). "None of the other investigated interleukins (IL-1β and IL-8) and TNF-α showed any differences in the serum of endometriosis patients in any comparison." (PMID 40724945, 2025). "We found elevated levels of HO-1 along with IL-10 and the pro-inflammatory cytokines (IL-1β, IL-16, IFNγ) in PM but not in PBMC from endometriosis patients." (PMID 35565370, 2022). "Reduction of IL-1R1 in the eutopic endometrium of baboons with induced endometriosis may increase the proliferative index of the endometrium; furthermore, aberration of αvβ3 expression seen in women with endometriosis may be mediated by the reduction of IL-1β signaling in the absence of IL-1R1." (PMID 17118171, 2006).
injury (189 papers, 2010 to 2026). Damage inflicted on the body as the direct or indirect result of an external force, with or without disruption of structural continuity. "This is in accordance with previous studies that underlined the importance of IL-1β and IL-18 in mediating the PA-induced acute lung injury and activation of NLRP3 inflammasome." (PMID 36463179, 2022). "Proinflammatory cytokines, such as interleukin (IL)-1a and IL-1b, are implicated in the molecular cascade leading to neuronal injury after brain trauma." (PMID 32164605, 2020). "Activated M1 phenotype microglia produce proinflammatory cytokines such as TNF-α, IL-1β, and IL-6; M2 phenotype microglia produce brain-derived neurotrophic factor and IL-10, which has been associated with neuroprotection after brain injury." (PMID 28529954, 2017). "Reduced renal IL-1β levels were in concordance with a previous study where TLR9 deficiency reduced the expression of IL-1β in a model of acetaminophen-induced liver injury." (PMID 26361210, 2015). "In traumatic brain injury the presence of low concentrations of IL-6 [IL-6 knock-out (KO) mice] is associated with poor behavior performance, and impacts the expression of IL1β, another powerful pro-inflammatory cytokine." (PMID 24133408, 2013). "Indeed, the inhibition of IL-1β or IL-6 signalling has demonstrated efficacy in alleviating neuropathic pain caused by nerve injury, underscoring the crucial involvement of IL-1β and IL-6 in the pathogenesis of neuropathic pain." (PMID 38390212, 2024). "Importantly, decreased serum level of TNFα and Il-1β in SCI patients after 9 h following injury correlated with the American Spinal Injury Association’s (ASIA) impairment scale (AIS) improvement." (PMID 36289607, 2022). "Furthermore, the activation of NLRP3 is closely associated with secretion of mature-IL-1β and cleave-caspase-1, which are closely related to the pathogenesis of liver injury." (PMID 33364966, 2020). "For example, neutralizing IL-1b could reduce cerebral edema and tissue loss causing an improvement in late cognitive outcome following traumatic brain injury in mice." (PMID 25257527, 2014). "However, excessive training with insufficient recovery causes musculoskeletal trauma with increased production of pro-inflammatory cytokines such as IL-1β, IL-6, and TNF-α, which contributes to symptoms related to performance decrement and exercise-induced fatigue." (PMID 31616260, 2019). "Other studies have also shown that paeoniflorin could protect mice against Bacillus Calmette-Guerin or lipopolysaccharide-induced liver injury, which might be associated with the effects of inhibition of IL-1β and TNF-α release and the promotion of IL-10 production." (PMID 27525026, 2016). "Specifically, NP cells from trauma patients exhibited a significant increase of catabolic, inflammatory, and mechanotransduction mediators under IL‐1β stimulation, similar to previous studies." (PMID 39931581, 2025). "Pro-inflammatory cytokines, including TNF-α and IL-1β, are key mediators of neuropathic pain and contribute to central sensitization following nerve injury." (PMID 40806499, 2025). "The Canakinumab Anti-Inflammatory Thrombosis Outcomes Study (CANTOS) demonstrated that IL-1β blockade significantly reduced cardiovascular events, highlighting its relevance in post-traumatic myocardial injury." (PMID 40710793, 2025). "In this study, treatment with CAG decreased the levels of TNF-α, IL-6, and IL-1β, suppressing inflammatory response and alleviating alcohol-induced liver injury." (PMID 40822494, 2025). "It has been reported that HMGB1 is positively associated with changes in LOX-1, IL-1β, and TNF-α in murine models of COPD and acute lung injury." (PMID 38655086, 2024). "Previous studies have shown that Tau reduces the secretion of pro-inflammatory cytokines, such as TNF-α, NF-κB, and IL-1β, in bleomycin-, endotoxin-, and cigarette smoke- induced acute lung injury." (PMID 39457890, 2024).
injury (continued). "Increased expression levels of inflammatory cytokines, such as TNF-α and IL-1β, have been reported in cisplatin-induced kidney injury in mice." (PMID 38890434, 2024). "TNF-α and IL-1β are important in mediating nerve injury-induced glial activation and enhancing synaptic transmission." (PMID 37639183, 2024). "The protective effects were also induced by CHBP on decreasing the formation of NLRP3 inflammasome and the secretion of IL‐1β via the NF‐κB pathway in LPS‐induced acute lung injury." (PMID 39584501, 2024). "Resveratrol alone has been shown to induce autophagy and evoke anti-inflammatory responses in retinal pigment epithelium cells, as well as inhibit NLRP3 inflammasome expression, caspase-1 activation, and IL-1β secretion in a mouse model of acute lung injury." (PMID 37375772, 2023). "Previous research on the APR blend has shown protective effects in a mouse model of LPS-induced acute lung injury, associated with down-regulation of the pro-inflammatory cytokines TNF-α, Interleukin-1 beta (IL-1β), and Interleukin-6 (IL-6)." (PMID 37699014, 2023). "Previous studies proved that IL-1β and IL-18 induced nerve injury and impaired the function of neurons." (PMID 37144237, 2023). "Paeonol, a physiologically active component of Moutan Radicis Cortex, has been reported to have anti-inflammatory and anticoagulant effects in an LPS-induced acute lung injury rat model and to reduce IL-1β levels in the BALF of cigarette smoke-induced mice." (PMID 37687271, 2023). "MMP9 loss facilitated pulmonary cell death and aggravated lung injury in an interleukin-1β (IL-1β)-induced lung injury mouse model." (PMID 36387401, 2022). "Based on these findings, IL-1β preconditioning is a viable option to enhance sEV functions and prevent LPS-induced lung injury." (PMID 35681240, 2022). "Pretreatment with Bacillus species spores (B. licheniformis, B. indicus, B. subtilis, B. clausii, and B. coagulans) lowered the serum levels of pro-inflammatory cytokines (TNF-α and IL-1β) against acetaminophen-induced acute liver injury in rats." (PMID 35799262, 2022). "BLM-induced acute lung injury was associated with a significant increase in the mean concentration of TNF-α, IL-6, IL-1B, and NF-kB in lung tissues compared to that in the control (p < 0.05)." (PMID 36500388, 2022). "Our cytokine analysis, using Simoa® technology, demonstrated robust decreases in IL-1β and IL-6, which, in light of the existing literature on head trauma, are quite paradoxical." (PMID 35785366, 2022). "Expressions of TNF-α, IL-1β, IL-6, and IL-8 cytokines in rats with acute lung injury induced by oleic acid were downregulated in the TCZ and DEX groups compared to the OA group (P < 0.05)." (PMID 36115998, 2022). "In a study of myocardial ischemia-reperfusion injury, researchers found that Puerarin can reduce the expression of inflammatory cytokines IL-6, IL-1β, and TNF-α through AMPK/Akt/GSK-3β /Nrf2 signaling pathway to prevent myocardial ischemia-reperfusion injury." (PMID 35482440, 2022). "demonstrating reduced expressions of Tnf-α and Il-1β in the lungs in a combined model of traumatic brain injury model with acute EI." (PMID 35663960, 2022). "The proinflammatory cytokine IL-1β is one of the most potent hyperalgesic agents released during peripheral trauma or nerve injury that increases the brain’s nociceptive signals." (PMID 35806360, 2022). "Inflammasome activation was further confirmed by detection of increased levels of cleaved IL-1β (i.e., the active form) in the spinal cord after nerve injury, which was inhibited by both 5-BDBD and MCC950." (PMID 35305649, 2022). "In particular, lutein and zeaxanthin reduced cytokines (IL-1β, IL-6) and NF-κB levels probably activating the Nrf2 pathway in a mouse model of traumatic brain injury." (PMID 34206804, 2021).
injury (continued). "Previous studies have suggested that the levels of tumor necrosis factor α (TNF-α), nuclear factor (NF-κB), interleukin 1β (IL-1β), and IL-6 increase in the bronchoalveolar lavage fluid of experimental rats with acute PQ-induced lung injury." (PMID 34580234, 2021). "Anakinra is a powerful inhibitor of both IL-1a and IL-1b, and IL-1b processed through the NLRP3 inflammasome activation has been shown to be involved in coronaviruses-related lung injuries." (PMID 33384683, 2020). "We also verified in this study that chondrocyte senescence and an imbalance in ECM homeostasis were obviously induced by IL-1β stimulation in vitro and by joint trauma in vivo." (PMID 31790972, 2020). "RosA significantly reduced LPS-induced TNF-α, IL-6, and IL-1β production; RosA plays an anti-inflammatory effect on the acute lung injury in mice by inhibiting ERK/MAPK signaling in a dose-dependent manner." (PMID 32184728, 2020). "Evidence suggested that LPS-toll-like receptor 4 signaling potentiates IL-1β release and subsequently upregulates IL-1RI expression on the surface of macrophages in acute lung injury model." (PMID 33081813, 2020). "Recent studies have shown that the activation of the NLRP3 inflammasome is a critical mediator responsible for the maturation of IL-1β for the development of acute lung injury." (PMID 32110933, 2020). "In fact, NLRP3 activation has been demonstrated to contribute to multiple diseases by increasing IL-1β and IL-18 secretion and amplifying the inflammatory response, including acute lung injury and acute liver failure." (PMID 32695257, 2020). "Stimulating cells with either IL-1β or sera from trauma patients induced a strong release of IL-6 as well as increased neutrophil adhesion to epithelial cells." (PMID 31739600, 2019). "Further studies are needed to show if stimulation of MSC with IL1B is a suitable in vitro model for specific local inflammatory responses, such as acute heart injury." (PMID 31086407, 2019). "In mice, levels of TNF-α, IL-1β, and IL-6 show an early rise (peaking at 2–4 h after aggression) in a lipopolysaccharide-induced lung injury model." (PMID 29515461, 2018). "PQ activates the NF-κB signaling pathway, resulting in the release of TNF-α, IL-1β, and IL-6 and leading to acute lung injury." (PMID 29566055, 2018). "It has hepatoprotective, anti-inflammatory and anti-cancer activity, and improves histological status and decreases serum ALT and IL-1β in the treatment of hepatic ischemia–reperfusion injury." (PMID 29636693, 2018). "We evaluated TNF-α, IL-6, and IL-1β, the major mediators in ConA-induced liver injury, and found that their expression was consistent with the extent of necrosis, apoptosis, and autophagy." (PMID 30116260, 2018). "Studies have confirmed that maresin 1 can suppress neutrophil infiltration and adhesion and reduce proinflammatory mediators such as TNF-α, IL-1β, and IL-6 in mice induced by acute lung injury." (PMID 28182085, 2017). "For example, AM suppresses the in vitro secretion and gene transcription of TNF-α and IL-6 in the murine monocyte/macrophage cell line RAW 264.7 and also attenuates TNF-α and IL-1β production in an in vivo acute lung injury mouse model." (PMID 28299347, 2017). "This is supported by the fact that synthetic PIF reduces the inflammasome response and NALP-3 induced IL-18 and IL-1β impact the pathogenesis of preeclampsia, preterm birth, and perinatal brain injury." (PMID 28704412, 2017). "In the present study, we reported that the expression of Sirt1 was downregulated after brain injury in vivo; a similar result was obtained in primary astrocytes after stimulation with IL-1β in vitro." (PMID 28356158, 2017). "It has been shown that various inflammatory cytokines, such as IL-1β and IL-6, produced during drug-induced liver injury are involved in promoting further liver tissue damage, so we next evaluated serum levels of IL-1β and IL-6." (PMID 28481246, 2017).
injury (continued). "IL-1β production increased abruptly and reached its peak within 1 day after nerve injury and maintained at higher levels than the sham group through 7 days PO." (PMID 27342775, 2016). "Chest trauma led to elevated expression levels of inflammatory and coagulatory proteins (such as TNFα receptor, IL-1α, IL-1β, C3, NF-κB and plasminogen activator)." (PMID 26303896, 2015). "For example, resolvin E1 can decrease the levels of IL-6 and IL-1β found in lung tissue following HCl-induced acute lung injury." (PMID 23663457, 2013). "Previous study has suggested that IL-1β plays an important role in mediating LPS-induced brain injury." (PMID 22844396, 2012). "IL-1β plays a role in development of neuronal cell death after traumatic, ischemic, excitotoxic, and seizure-induced brain injury." (PMID 20939924, 2010). "In our study, the reduced IL-1β cleavage in the sciatic nerve following MP-10 treatment further supported the idea that PDE10A inhibition modulates inflammasome activation in nerve injury, contributing to improved functional recovery and reduced muscle atrophy." (PMID 40429643, 2025). "In a rat acute lung injury model, taurine could reduce the content of pro-inflammatory cytokines IL-1β and interleukin-6 (IL-6), alleviate pulmonary inflammatory response, and demonstrate therapeutic potential for acute lung injury." (PMID 41380328, 2025). "Su’s study demonstrated that Yinchen and a Gancao Decoction significantly reduced the expression levels of IL-1β, IL-6, and TNF-α in the hepatocyte and revealed that hepatocyte necrosis caused by cholestatic liver injury can be alleviated by reducing the release of inflammatory cytokines." (PMID 41471340, 2025). "Moreover, we demonstrated that dasatinib treatment effectively ameliorated inflammatory manifestations in SP-induced acute lung injury in mice, characterized by the increased levels of IL-1α, IL-1β, CXCL1, neutrophils, and M1 macrophages." (PMID 37705538, 2023). "Previous studies had demonstrated that Rspo2 could mitigate inflammation response in IL-1β-treated chondrocytes and regulate inflammation response in acute ozone-induced lung injury." (PMID 37946278, 2023). "In addition, we suggest that pretreatment with TNF-α and IL-1β directly enhances the immune regulation ability of hADSCs against hepatic inflammation and restrains the adverse consequence of cholestatic liver injury." (PMID 37095581, 2023). "Other animal models have shown that hypothermia can reduce the injury area and have direct effects on levels of IL-1β after traumatic brain injury, thereby indicating the beneficial effects of CT to be at least partly due to decrease of expression of inflammatory mediators." (PMID 36451020, 2023). "Such a decrease may be correlated to neuronal injury through the release of chemical messengers induced by brain injury and microglia activation, such as IL-1β." (PMID 36613467, 2022). "Moreover, TA was found to inhibit inflammatory response and apoptosis through attenuation of TNF-α, IL-1β, IL-6, Bax, Bcl-2, and caspase-3 in CCl4-induced liver injury in mice." (PMID 36358896, 2022). "Similarly, p38MAPK mediates LPS-induced morphological changes and production of IL-1β in primary microglial cultures and the brain, and it contributes to acute lung injury in a mouse model by stimulating autophagy, oxidative stress and inflammatory responses." (PMID 34711216, 2021). "Studies have shown that the CM of bone marrow mesenchymal stem cells (BMSCs) reduced the serum concentrations of TNF-α, IL-1β and IL-6; in contrast, the level of the anti-inflammatory cytokine IL-10 significantly increased in rats with radiation-induced liver injury." (PMID 33781342, 2021). "A previous study reported that baicalin could diminish levels of pro-inflammatory mediators, TNF-α, IL-6 and IL-1β, in acute lung injury, functioning as a potential therapeutic candidate, which was largely consistent with the observations of our study." (PMID 34053448, 2021).